REG3A (regenerating family member 3 alpha)
Description:
[Regenerating islet-derived protein 3-alpha 15 kDa form]: Bactericidal C-type lectin which acts exclusively against Gram-positive bacteria and mediates bacterial killing by binding to surface-exposed carbohydrate moieties of peptidoglycan. Binds membrane phospholipids and kills bacteria by forming a hexameric membrane-permeabilizing oligomeric pore. Acts as a hormone in response to different stimuli like anti-inflammatory signals, such as IL17A, or gut microbiome. Secreted by different cell types to activate its receptor EXTL3 and induce cell specific signaling pathways. Induced by IL17A in keratinocytes, regulates keratinocyte proliferation and differentiation after skin injury via activation of EXTL3-PI3K-AKT signaling pathway. In parallel, inhibits skin inflammation through the inhibition of inflammatory cytokines such as IL6 and TNF. In pancreas, is able to permealize beta-cells membrane and stimulate their proliferation. [Regenerating islet-derived protein 3-alpha 16.5 kDa form]: Has bacteriostatic activity.
Synonyms: HIP/PAP; HIP; PAP; PAP1; REG-III; REG3; PBCGF; INGAP; PAP-H
Tractability: Antibody: UniProt places it where antibodies can reach, with high confidence; its Gene Ontology location is reachable by antibodies, with high confidence; UniProt predicts a signal peptide or a membrane-spanning region.
Gene: Protein-coding gene on chromosome 2 (79,157,003 to 79,159,753, reverse strand). Ensembl gene ENSG00000172016.
Subcellular location: Secreted
Subcellular location (Human Protein Atlas): Cytosol; Predicted to be secreted
Pathways (Reactome):
Immune System: Antimicrobial peptides
Gene Ontology:
Molecular function: hormone activity; identical protein binding; protein binding; carbohydrate binding; growth factor activity
Biological process: negative regulation of inflammatory response to wounding; negative regulation of keratinocyte differentiation; positive regulation of keratinocyte proliferation; response to wounding; antimicrobial humoral immune response mediated by antimicrobial peptide; heterophilic cell-cell adhesion; negative regulation of inflammatory response; positive regulation of cell population proliferation; positive regulation of detection of glucose; positive regulation of wound healing; response to peptide hormone; response to symbiotic bacterium; signal transduction
Cellular component: extracellular region; cytoplasm
Genetic constraint (gnomAD): Loss-of-function variants: 16 observed, 21.78 expected, observed/expected ratio (o/e) 0.73, 90% interval 0.5 to 1.12. The upper end of that interval is the gene's LOEUF score, 1.12, which puts it in group 4 of 6, group 1 being the genes least tolerant of losing a copy. Missense variants: 224 observed, 220.58 expected, observed/expected ratio (o/e) 1.02, 90% interval 0.91 to 1.13. Synonymous variants: 93 observed, 86.43 expected, observed/expected ratio (o/e) 1.08, 90% interval 0.91 to 1.28.
Homologues: Orthologues: chimpanzee REG3A (98% identical), macaque REG3A (93% identical), dog REG3A (74% identical), zebrafish si:dkey-241l7.4 (29% identical), zebrafish si:dkey-241l7.2 (28% identical), zebrafish si:dkey-241l7.3 (28% identical), zebrafish zgc:172053 (28% identical), zebrafish si:ch211-125e6.5 (27% identical), zebrafish si:dkey-241l7.5 (27% identical), zebrafish si:dkey-241l7.6 (27% identical), zebrafish si:ch211-125e6.11 (26% identical), zebrafish si:ch211-125e6.12 (26% identical), and 10 more. Paralogues in human: REG3G (85% identical), REG1A (49% identical), REG1B (46% identical), REG4 (31% identical), CLEC19A (30% identical).
Diseases named in the same sentence as REG3A in open-access papers:
REG3A is named in the same sentence as 97 diseases in open-access papers, as found by Europe PMC text mining. Sharing a sentence is not in itself a finding about the gene and the disease. The quoted sentences say what the papers report.
pancreatic cancer (21 papers, 2013 to 2025). "Along the same lines, REG3A was linked to the activation of the JAK2-STAT3 pathway in pancreatic cancer cell lines and of the MAPK in acinar cells." (PMID 31696115, 2019). "Silencing SOCS3 enhances REG3A-driven tumor progression, while its overexpression suppresses malignancy across multiple pancreatic cancer cell lines." (PMID 40723277, 2025). "Eckol, for example, has been shown to inhibit Reg3A-induced proliferation in human pancreatic cancer cells, effectively suppressing downstream signaling pathways." (PMID 39857608, 2024). "This was consistent with the role of Reg3A in pancreatic cancer, where it drove tumor development via an IL6-JAK/STAT3-Reg positive feedback loop." (PMID 39857608, 2024). "Activation of the Reg3A gene alters the JAK2/STAT3 pathway in pancreatic cancer cells, which can increase the expression of REG3A gene, forming a positive feedback mechanism to further promote the expression of REG3A in tumor cells." (PMID 37505298, 2024). "REG1A, REG1B, and REG3A were reported to be increased in cancer ductal fluid, and REG1A was linked to pancreatic cancer." (PMID 37107224, 2023). "The biological importance of the Reg3A protein is evident in the influence on pancreatic cancer cells’ proliferation and progression, additionally with the appearance of an inflammatory microenvironment." (PMID 35209235, 2022). "In Reg family proteins, human Reg3A is involved in a Reg3A-Jak2/Stat3 positive feedback loop in pancreatic cancer cells and mouse Reg3α and Reg4 have crosstalk with EGFR/Akt pathway." (PMID 36142497, 2022). "In patients with pancreatic cancer (PaC), REG3A overexpression coexisted with SOCS3 methylation to promote PaC cell growth through the JAK/STAT3/NF-κB signaling pathway." (PMID 34811636, 2022). "REG3A has been described as a proliferating factor following liver and skin injuries as well as a driver of pancreatic cancer cell growth through JAK2/STAT3 signaling pathways in response to interleukin-616,18." (PMID 34099862, 2021). "• siRNA-mediated SOCS3 knock-down in normal pancreatic HPDE6C7 cells and plasmid-transfected SOCS3 over-expression in pancreatic cancer cells lead to the obvious promotion and inhibition of Reg3A-induced cell proliferation, respectively." (PMID 31921694, 2019). "• AG-490 treatment to block JAK2 inhibited Reg3A up-regulated expression of pJAK2 and pSTAT3 in pancreatic cancer SW1990, AsPC-1 cells and pancreatic epithelial HPDE6C7 cells." (PMID 31921694, 2019). "It is suggested that REG3A synergistically with interleukins (e.g., IL-6) promotes proliferation of pancreatic cancer cells via a REG3A-JAK2-STAT3 positive feedback loop." (PMID 31696115, 2019). "And Reg3A over-expression in pancreatic cancer was significantly correlated with nodal involvement, distant metastasis and short survival." (PMID 31921694, 2019). "• Exogenous Reg3A notably enhanced the STAT3 activation by phosphorylation in pancreatic cancer MiaPaCa2 and Panc1 cells." (PMID 31921694, 2019). "According to our previous study, EGFR, functioning as a REG3A receptor, mediated the REG3A signal-promoting human pancreatic cancer cell growth and JAK2/STAT3 activation." (PMID 28880262, 2017). "From the table, REG3A mainly exhibited differential expression and function in malignant tumors, over-expressed REG3A has been mostly found in the digestive system cancer, including hepatocellular carcinoma, pancreatic cancer, gastric cancer, and colorectal cancer." (PMID 34811636, 2022). "Moreover, phlorotannin 2 significantly inhibited the growth of the pancreatic cancer cell line induced by the presence of an exogenous regenerating gene protein (Reg3A)." (PMID 35209235, 2022). "Since 1998, REG3A has been discovered to be expressed in various tumor cells and tissues, including in gastric cancer, breast cancer, glioma, pancreatic ductal adenocarcinoma, hepatocellular carcinoma, colorectal carcinoma, and pancreatic cancer." (PMID 34811636, 2022).
pancreatic cancer (continued). "The expression of Reg3A was significantly upregulated in pancreatic, liver, and colorectal cancer in humans, while significant upregulation of Reg3G has been specifically noted in pancreatic cancer." (PMID 33027970, 2020). "Reg3A and G have been involved in the development and progression of pancreatic cancer." (PMID 33027970, 2020). "In the present study, we firstly detected a key molecule, the Reg3A/G, which might be involved in this phenomenon and could be a target for the prevention of periodontal-related pancreatic cancer." (PMID 33027970, 2020). "The upregulated expression levels of Reg3A and G might play a key role in PG-LPS-related pancreatic cancer in mouse." (PMID 33027970, 2020). "The upregulated expression levels of Reg3A/G stimulated with PG-LPS in the present study imply that these proteins may be key for periodontal disease-related pancreatic cancer in human." (PMID 33027970, 2020). "In summary, the overexpression of Reg3A, a protein mainly expressed in the digestive system, has been demonstrated in many kinds of gastrointestinal cancer, including hepatocellular carcinoma, pancreatic cancer, gastric cancer, and colorectal cancer." (PMID 31921694, 2019). "Accumulating evidence has clarified the role of Reg3A in the development of pancreatic cancer." (PMID 31921694, 2019). "Whereas, a decrease in proliferation was observed in Reg3A siRNA-treated pancreatic cancer cells." (PMID 31921694, 2019). "However, the pancreatic-specific expression of Reg3A let many researchers focus their attention on its relationship to the pancreatic cancer." (PMID 31921694, 2019). "In human pancreatic cancer cell lines, incubation with exogenous Reg3A dramatically promoted the cell proliferation, the soft-agarose colony forming ability, the transcript levels of cell cycle regulatory switch Cyclin D1, decreased cell numbers at G0/G1 phase, and increased cell numbers at S phase." (PMID 31921694, 2019). "To validate whether Reg3g, the mouse homolog of human REG3A, modulates pancreatic tumor growth via alteration of the TME composition in vivo, we established Reg3g-conditioned Panc02 cells, which exhibited upregulated Reg3g, and then implanted them into mice." (PMID 28880262, 2017). "Furthermore, a positive feedback loop involving Reg3α-JAK/STAT-3 has been confirmed to accelerate pancreatic cancer cell growth." (PMID 27767186, 2016). "Therefore, the up-regulation of Reg3A might act as one of the engines for the transformation from pancreatitis to pancreatic cancer." (PMID 31921694, 2019). "Relevant studies have shown that REG3A acts as a growth-promoting cell regulator and interacts with JAK2/STAT3 signaling to form a positive feedback loop to accelerate pancreatic cancer cell growth under IL-6-related inflammatory conditions." (PMID 36105933, 2022). "In pancreatic cancer cell line SW1990 or BxPC-3, flow cytometry analysis showed a dramatically high level of apoptosis after silencing endogenous Reg3A using siRNA." (PMID 31921694, 2019). "Additionally, it appears that eckol reverted the Reg3A-mediated upregulation of JAK2, STAT3, NF-κB and cyclin D1, proteins involved in signaling pathways related to the proliferation, migration and apoptosis of cells, promoting a reduced proliferation of pancreatic cancer cells." (PMID 35736190, 2022).
gastric cancer (14 papers, 2018 to 2025). A primary or metastatic malignant neoplasm involving the stomach. "REG3A is a member of the Reg protein family and other members of the Reg protein family are associated with human gastric cancers." (PMID 31940813, 2020). "Functional analyses further reveal that REG3A overexpression inhibits proliferation and induces apoptosis in gastric cancer cell lines, largely through modulation of the PI3K/Akt signaling pathway and upregulation of DMBT1, a known tumor suppressor." (PMID 40723277, 2025). "In gastric cancer (GC), several studies report a significant downregulation of REG3A in tumor tissues, implying a tumor-suppressive function." (PMID 40723277, 2025). "In gastric cancer, Reg1α promoted angiogenesis via the classical Akt and Erk signaling pathways, while Reg3A enhanced cell viability and drug resistance in ovarian cancer by activating the Akt signaling pathway." (PMID 39857608, 2024). "• The phosphorylation of GSK3β was significantly suppressed by Reg3A overexpression, whereas, was obviously increased in Reg3A-silenced gastric cancer HGC-27 cells." (PMID 31921694, 2019). "• The phosphorylation of Akt was significantly suppressed by Reg3A overexpression, whereas, was obviously increased in Reg3A-silenced gastric cancer HGC-27 cells." (PMID 31921694, 2019). "To date, no further studies have been reported that could clarify the role of REG3A in gastric cancer." (PMID 40723277, 2025). "Similarly, Reg3A inhibited the proliferation of gastric cancer cells via the PI3K/Akt-GSK3β pathway and promoted apoptosis by up-regulating DMBT1." (PMID 39857608, 2024). "Interestingly, REG3A was reported to suppress gastric cancer cell invasion and proliferation through the PI3K/AKT signaling pathway." (PMID 36986671, 2023). "REG3A expression was also significantly reduced in primary human breast and gastric cancers." (PMID 34811636, 2022). "In primary human gastric cancers, REG3A was found to be downregulated in 67% (20 out of 30) samples and could be restored by the demethylating agent 5-Aza-dC, indicating that the loss of REG3A may be associated with DNA methylation." (PMID 34811636, 2022). "We could notice that the expression of REG3A in gastric cancer exhibited inconsistent in different research groups." (PMID 34811636, 2022). "In gastric cancer, previous studies have reported the effect of Reg3A on cell biological function." (PMID 34605357, 2021). "The Reg3A expression had also been investigated in gastric cancer samples." (PMID 31921694, 2019). "The epigenetic inactivation of Reg3A was presumed to occur during tumorigenesis in gastric cancer." (PMID 31921694, 2019). "Therefore, further researches enrolling large clinical samples of gastric cancer patients and systemic epigenetic studies would help to clarify the expression status of Reg3A in gastric cancer." (PMID 31921694, 2019). "Nevertheless, there appears to be a mixed expression profile of Reg3A in gastric cancer." (PMID 31921694, 2019). "The REG3A gene has been reported to be downregulated in gastric cancers and may be involved in cell adhesion and protection from oxidative stress-induced apoptosis." (PMID 29484116, 2018). "However, low-expressed REG3A was found in gastric cancer and breast cancer." (PMID 34811636, 2022). "However, the function and downstream regulatory mechanism of Reg3A in gastric cancer (GC) remains elusive." (PMID 34605357, 2021). "The same analysis methods were applied in gastric cancer line SGC-7901 cells, and the results also revealed that Reg3A promoted the gastric cancer cell invasion and migration." (PMID 31921694, 2019). "REG3A has been shown to have pro-tumorigenic effects, including promotion of cell proliferation, inhibition of cell apoptosis, and regulation of cancer cell migration by activating AKT and ERK1/2 pathways in gastric cancer cells." (PMID 35927305, 2022).
gastric cancer (continued). "Auto-antibodies against Reg3A had been detected in none of the healthy donors but in 22.9% of the gastric cancer patients." (PMID 31921694, 2019).
pancreatitis (14 papers, 2006 to 2024). Inflammation of the pancreas. "REG3A is overexpressed in pancreas and small intestine and has been associated with cystic fibrosis and pancreatitis." (PMID 28974199, 2017). "Reg3 subfamily, including Reg3A and Reg3G, are known as pancreatitis-associated proteins due to their activation in response to inflammatory stimuli." (PMID 27788482, 2016). "Three genes, linked to pancreatitis and cancer, the regenerating islet-derived 3 alpha, beta and gamma (Reg3a, Reg3b and Reg3g), were increased by more than 100-fold by AMPH within 3 hr, but not by EIH." (PMID 23497014, 2013). "Regenerating islet-derived protein (REG) 1A (aka pancreatic stone protein) and REG3A (aka pancreatitis-associated protein) are upregulated in humans with sepsis, pancreatitis, and gastrointestinal diseases, but little is known about this protein family in dogs." (PMID 36387376, 2022). "Islet-derived protein 3A (Reg3A), a kind of protein in the REG protein family, is known as liver tumor-gut-pancreas-associated protein or human pancreatitis-associated protein." (PMID 37505298, 2024). "The specific knockout of Reg3b or administration of anti-Reg1, anti-Reg3a, and anti-Reg4 antibodies worsen experimental pancreatitis, while administration of recombinant Reg3a and Reg4 can significantly reduce the pancreatic damage." (PMID 37500741, 2023). "The resulting elevated blood concentration of REG3A has been proposed as a possible prognostic biomarker for many human acute and chronic diseases, including pancreatitis, inflammatory bowel disease, graft versus host disease, and ischemic stroke." (PMID 36918710, 2023). "The involvement of Reg3A has been demonstrated in several disease conditions, such as pancreatitis, diabetes, skin inflammation and injury, and inflammatory bowel disease." (PMID 31921694, 2019). "Known as pancreatitis-associated protein, Reg3A is sensitively and markedly induced after the onset of pancreatitis, which is manifested as the 200- to 300-fold increase in Reg3A expression level after even mild pancreatic inflammation." (PMID 31921694, 2019). "In wild type mice induction of pancreatitis transiently reduced the protein amounts of Reg3α similar to the changes in mRNA levels." (PMID 16700916, 2006). "When pancreatitis was induced, staining for Reg3α was variable and there were areas of strong reactivity in the tissue at different times." (PMID 16700916, 2006). "During pancreatitis in CF mice, Reg3α staining was variable and there were some strongly stained regions adjacent to weakly stained areas (1 h) or more uniformly labeled tissue (7 h)." (PMID 16700916, 2006). "Immunohistochemical staining for Reg3α was used to visualize expression patterns in wild type and CF mice, under control conditions and during pancreatitis." (PMID 16700916, 2006). "During pancreatitis, Reg3α was intensely expressed in foci of inflamed tissue in both wild type and CF." (PMID 16700916, 2006). "Similar foci of Reg3α immunoreactivity have been previously noted in areas of inflammation in caerulein-induced experimental pancreatitis in rats." (PMID 16700916, 2006). "When pancreatitis was induced in CF mice the levels of Reg3α protein changed little, in contrast to more substantial changes in mRNA." (PMID 16700916, 2006). "Besides sepsis, serum levels of REG1A and REG3A are increased in people with pancreatitis, as well as gastrointestinal pathologies, such as inflammatory bowel disease and colorectal carcinoma." (PMID 36387376, 2022). "Moreover, a proteomic analysis of pancreatic juice demonstrated increased levels of Reg1A, Reg1B and Reg3A proteins in PDAC, in comparison to normal subjects and patients with pancreatitis." (PMID 27788482, 2016). "Despite the finding that Reg3α was highly expressed in the control CF mouse pancreas and that protein levels did not change dramatically during pancreatitis, there were differences in the expression pattern by immunohistochemistry." (PMID 16700916, 2006).